AQP4 (aquaporin 4)
Diseases named in the same sentence as AQP4 in open-access papers (continued):
Sharing a sentence is not in itself a finding about the gene and the disease.
Alzheimer disease (continued). "In a mouse model of Alzheimer Disease (Tg-ArcSwe mouse) changes in AQP4 expression are evident at the early stages of plaque formation, indicating that a loss of astrocytic AQP4 polarization could play a key role in the pathogenesis of the disease." (PMID 27503424, 2016). "Therefore, maintaining and supporting AQP4 function might protect against neurodegenerative diseases such as Alzheimer’s disease." (PMID 36920936, 2023). "While the linkage of high levels of AQP4 to Alzheimer ́s Disease are tantalizing, it may not be a primary mechanism of pathology as AQP4 deletion has also been associated with increased protein accumulation, most notably after TBI." (PMID 36859364, 2023). "Therefore, enhancing AQP4 function might protect against neurodegenerative diseases such as Alzheimer’s disease (AD), in which the accumulation of harmful proteins and solutes is a hallmark feature." (PMID 36920936, 2023). "Previous studies have shown that AQP4 can be secreted into peripheral blood through brain‐derived plasma exosomes thus elevating AQP4 expression can be detected in peripheral blood, in case of CNS disorders such as Alzheimer's disease and traumatic brain injury and so on." (PMID 36922751, 2023). "It suggests that AQP4 may serve as a significant predictor for the status of certain diseases, including chronic sleep disruption, Alzheimer’s disease (AD), and traumatic brain injury (TBI), whose pathogeneses are all related to the inefficient waste removal process." (PMID 35173581, 2021). "Aquaporin-4 (AQP4) has been suggested to be involved in the pathogenesis of neurodegenerative diseases including Alzheimer’s disease (AD), which may be due to the modulation of neuroinflammation or the impairment of interstitial fluid bulk flow system in the central nervous system." (PMID 32398151, 2020). "AQP4 may be involved in Alzheimer's disease by facilitating clearance of neurotoxic amyloid ß (Aß)." (PMID 32765412, 2020). "It has also been shown that the appropriate expression pattern of AQP4 polarization to astrocytic endfeet is required for efficient glymphatic CSF-ISF exchange, and that this polarization in the brain declines with age, the greatest risk factor for developing Alzheimer’s disease." (PMID 32705145, 2020). "Altered AQP4 has been shown to contribute to cerebral edema in various neurological conditions, including not only HE associated with ALF but also focal traumatic brain injury (TBI), ischemic stroke, influenza-associated encephalopathy, and Alzheimer’s disease (AD)." (PMID 29216295, 2017). "Reductions in aquaporin (AQP4) expression in the astrocytic foot processes have been observed in brain tissue in NPH and Alzheimer’s Disease (AD) patients." (PMID 40376155, 2025). "Interestingly, chronic stress may also reduce AQP4 levels, impairing glymphatic clearance and promoting β-amyloid (Aβ) accumulation, suggesting a mechanistic link between depression and neurodegenerative processes like Alzheimer’s disease." (PMID 40725164, 2025). "Interestingly, a recent AI-based study suggested that AQP4 may be involved in the pathological accumulation of β-amyloid in Alzheimer’s disease, with a sex-dependent effect on early brain amyloid aggregation, potentially influenced by an AQP4 polymorphism-based risk score." (PMID 41009480, 2025). "AQP4 appears to be involved in the removal of oedema fluid from the brain in a variety of disorders and enhancing AQP4 expression could be a therapeutic strategy for reducing dilated perivascular spaces and WMH associated with advancing age and Alzheimer’s disease." (PMID 32059400, 2020). "Our finding of impaired AQP4 polarization in affected regions of the tauopathy brain, and the effect of pharmacological AQP4 inhibition, suggest that this water channel may present as a novel target for modulation of this pathway for therapeutic effect in Alzheimer’s disease." (PMID 32705145, 2020).
Alzheimer disease (continued). "Using a streptozotocin (STZ)-induced Alzheimer's disease-like rat model, we conducted the current study to determine the effects of HIIT on AD pathologies and study the relationship between astrocyte polarization and AQP4 polarized distribution in AD." (PMID 37351177, 2023). "Here we study the glymphatic system using MRI, the clearance of parenchymal tau using intracerebral injections and CSF sampling, and the modulation of AQP4 function, in a mouse model that develops tau NFT pathology similar to that seen in neurodegenerative diseases such as Alzheimer’s disease." (PMID 32705145, 2020). "A clear picture of how the pattern of immunocytochemistry of AQP4 changes in the grey and white matter in health and disease will advance our knowledge of how best to target AQP4 for rebalancing levels of fluid and solutes in the brain in CAA and Alzheimer’s disease." (PMID 32059400, 2020). "This clinically relevant tool may be crucial to better understand the role of AQP4 in water transport across the BBI, as well as clearance of proteins in neurodegenerative conditions such as Alzheimer's disease." (PMID 30557661, 2019). "Despite the presence of evidences on the involvement of AQP4 in Alzheimer's disease, no specific drug is developed to target this molecule to date probably due to its poor druggability." (PMID 29888263, 2018). "Interestingly, the treatment of wild-type mice with amyloid β40 resulted in a significant reduction of CSF influx, pointing toward a negative AQP4-dependent reinforcement loop within Alzheimer’s disease." (PMID 36768495, 2023). "Alzheimer’s Disease (AD) is a notable example: a decade ago it was shown in a mouse model of AD that AQP4 was conspicuously absent from endfeet adjoining amyloid plaques, while more recent studies have demonstrated reduced amyloid clearance following targeted disruption of Aqp4." (PMID 35518645, 2022). "Cultured human postmortem astrocytes from Alzheimer disease (AD) increased GFAP reactivity and released EVs with increased Aquaporin 4 expression." (PMID 33679370, 2021). "Furthermore, deletion of AQP4 in APP/PS1 mice has been shown to potentiate the development of amyloid-β pathology and memory deficits, suggesting that supressed glymphatic clearance is capable of inducing and/or advancing Alzheimer’s disease pathology." (PMID 32705145, 2020). "Aß plaque accumulation is increased in the absence of AQP4 in a mouse model of Alzheimer's disease." (PMID 32765412, 2020). "The glymphatic system, that is aquaporin 4 (AQP4) facilitated exchange of CSF with interstitial fluid (ISF), may provide a clearance pathway for protein species such as amyloid-β and tau, which accumulate in the brain in Alzheimer’s disease." (PMID 32705145, 2020). "Our results also do not support a role for AQP4 in convection-driven clearance of beta amyloid, though they do not rule out the possibility that AQP4 may contribute to the pathology of Alzheimer’s disease in other ways." (PMID 28826498, 2017).
ischemia (100 papers, 2007 to 2025). A hypoperfusion of the BLOOD through an organ or tissue caused by a PATHOLOGIC CONSTRICTION or obstruction of its BLOOD VESSELS, or an absence of BLOOD CIRCULATION. "It was observed that the loss of function of AQP-4 led to CSF tracer distribution disturbance and it was proposed to be involved in Aβ clearance impairment and brain edema development in ischemia as well as brain tumors." (PMID 40464180, 2025). "AQP4 plays a critical role in regulating cerebral oedema, a pathology that is associated with ischemia." (PMID 40742699, 2025). "TTC staining results showed that the knockdown of AQP4 expression actually protected brain tissue in MCAO mice and reduced the damage caused by MCAO‐induced ischemia in brain tissue, which was completely opposite to the effect of AQP4." (PMID 39444081, 2024). "Regarding microglia and astrocytes, visualized by Iba, GFAP, and AQP4, the observed ischemia-associated alterations were in line with earlier reports exploring cellular changes due to ischemia." (PMID 35682557, 2022). "On the other hand, inhibition of aquaporin-4 is also known to cause astrocyte dysfunction, preventing recovery from ischemia." (PMID 34617156, 2021). "Another miRNA associated with both AQP4 and ischemia is miR-145, which was found to attenuate rAQP4-induced astrocyte injury in an in vitro oxygen-glucose deprivation model of ischemia in primary cultured rat astrocytes." (PMID 32111087, 2020). "Further, astrocytes have been shown to critically impact on the ischemia-associated edema formation which involves Aqp4 water channels." (PMID 30744693, 2019). "Applying this model, our group already described ischemia-associated changes in endothelial cells, up-regulation of Coll IV in basal membranes and loss of aquaporin 4 in astrocytic endfeet 24 h after ischemia induction." (PMID 28860977, 2017). "Its upregulation and redistribution in trauma, pneumococcal meningitis, glioblastoma or ischemia were associated with worse outcome, while edema was reduced with aquaporin-4 downregulation or deletion." (PMID 27690011, 2016). "The neuroinflammation produced by ischemia leads to upregulation of MMPs which cause AQP4-OAP disruption, and possibly exacerbate BBB disturbance and worsen the edema." (PMID 25904843, 2015). "This work suggested that AQP-4 inhibition might be used pharmacologically to reduce brain edema caused by localized ischemia." (PMID 40464180, 2025). "Studies used variant animal models of cerebral ischemia to examine ischemia-induced functional changes at different time points and the role of AQP4 in brain edema after IS and found that the inhibition of AQP4 reduced cerebral edema and improved motor recovery and long-term prognosis." (PMID 37065921, 2023). "Moreover, a recent study showed that impaired perivascular AQP4 covering after ischemia was associated with altered reactive astrocyte morphology and enhanced brain edema." (PMID 34305569, 2021). "In these models, AQP4 level increase caused by ischemia or ischemia-reperfusion injury could be attenuated by reducing cerebral temperature, albeit this effect seemed to be strongly dependent on rewarming conditions." (PMID 30333785, 2018). "As described by Blixt, in cytotoxic edema induced by ischemia, the amount of edema is reduced in AQP4 deficient animals, water accumulation is intracellular, and astrocytes, normally diffusely populated by AQP4 channels, would be protected from swelling in knockout models." (PMID 30423808, 2018). "Additionally, cerebral edema, one of the major consequences of ischemia, beginning with cytotoxic edema caused by the intracellular accumulation of Na+ and osmolytes, which is exacerbated by the overexpression of aquaporin-4 (AQP4), the main water channel in the central nervous system." (PMID 41465215, 2025).
ischemia (continued). "It is further unknown if the regulation of AQP4 cell-surface expression by Cav1 can significantly affect the cellular swelling associated with ischemia, especially given that this process may be dominated by osmotic gradients between oxidatively-stressed astrocytes and the extracellular space." (PMID 29326556, 2017). "Given that the maximal brain water content was found at 48 hours, and the deletion of perivascular AQP4 was found to alleviate edema formation after ischemia, the loss of AQP4 at the endfeet surrounding capillaries may be a protective response of the brain to reduce edema formation." (PMID 26526878, 2015). "Early after ischemia onset, during the acute phase characterized by cytotoxic edema, AQP4 facilitates rapid water influx into astrocytes, leading to cellular swelling." (PMID 40943104, 2025). "Expressing the water channel Aquaporin‐4 (AQP4), these cells have gained increasing attention for their roles not only in water homeostasis but also in neuroinflammation following ischemia." (PMID 39444081, 2024). "It has been well-documented that AQP4 plays an important role in brain edema formation under ischemia and trauma injury conditions." (PMID 36769234, 2023). "Under normal conditions, AQP4 is coexpressed around blood vessels in mouse brain tissue, and the distribution of AQP4 in the extravascular area increases after ischemia, suggesting the redistribution of AQP4 in mice after cerebral ischemia." (PMID 35685645, 2022). "Compared with the sham group, the ischemia group showed an increased level of AQP4 that peaked at 1 and 6 hre." (PMID 36605551, 2022). "AQP5 mRNA was shown to be downregulated in rat astrocytes after hypoxia treatment, and similar decreases in AQP5 expression but with concomitant increases in AQP4 expression were observed in an in vitro ischemia model of primary astrocyte cultures." (PMID 36010640, 2022). "Relative values of ADCst and ADCmh, AQP4 expression were compared between the sham group and the ischemia group." (PMID 36605551, 2022). "Overexpression of AQP4 has also been reported to reduce cytotoxic edema in a hypoxia-ischemia rat model." (PMID 36293145, 2022). "We found that Aqp4 upregulated at 12 h but vastly decreased at 24 h, possibly indicating self-protection of astrocytes from swelling and edema after ischemia." (PMID 35535357, 2022). "The continuous and dynamic observation carried out in transient MCAO demonstrated that AQP4 mRNA and protein were upregulated at 30 min after ischemia and that this lasted at least 72 h and normalized after 28 days." (PMID 34305569, 2021). "The decrease of the intracellular pH of the myocardial tissue and plasma in patients with a severe aortic stenosis after CPB was associated with ischemia and revealed that the expression of AQP-1 and AQP-4 was increased and a myocardial edema was induced." (PMID 34942981, 2021). "TGN-020 was shown in mouse models to significantly reduce AQP4-mediated edema following ischemia, but the molecule was administered before injury." (PMID 30934923, 2019). "Alterations in AQP4, a water channel protein that regulates water homeostasis, play an important role in ischemia-induced changes in BBB integrity." (PMID 29599893, 2018). "Aquaporin 4 (AQP4), the predominant water channel in the brain, is expressed in astrocyte endfeet and plays an important role in brain edema following ischemia." (PMID 28503134, 2017). "This biphasic AQP4 expression is consistent with the internalization and decomposition of AQP4 at 3 h after the onset of ischemia." (PMID 27242440, 2016). "The mechanism underlying this redistribution is unclear: While the M1 homodimer, the isoform that tends to reduce OAP size and Aqp4 polarization, trended upwards in cortical astrocytes, the M23:M1 ratio was largely unchanged after ischemia." (PMID 26419740, 2015). "Studies using AQP4- knockout mice (AQP-KO) and wild-type have aided in the elucidation of various roles of AQP4 in ischemia." (PMID 25904843, 2015).
ischemia (continued). "AQP4 modulation by metabotropic receptors or signaling chain stimuli, particularly inhibition of AQP4 up-regulation, offers a possible therapeutic avenue to minimize brain edema from the excessive glutamate that is released during ischemia." (PMID 25904843, 2015). "In many injury models of ischemia, the increase in AQP4 protein levels corresponds to the timing of BBB opening." (PMID 26526878, 2015). "Taken together, these results indicate that AQP4 mediates osmotically-driven water transport that follows ischemia." (PMID 25904843, 2015). "A central role of AQP4 in neuroinflammation is in the established astrocyte proliferative response in ischemia." (PMID 25904843, 2015). "Experiments showed that while AQP4 at the perivascular pool at the injury core was decreased after ischemia, the cortical border zone showed a slight increase in AQP4 at the same time." (PMID 26526878, 2015). "The disruption of AQP4 square array formation on the membrane 30 minutes after ischemia was observed." (PMID 26526878, 2015). "We found that, in contrast with astrocytes in the ischemic cortex, astrocytes in ischemic subcortical white matter exhibited increased perivascular endfoot Aqp4 following ischemia." (PMID 26419740, 2015). "In experimental rodent models of ischemia this prevents edema formation through decreases in AQP4 expression." (PMID 25904843, 2015). "AQP4 expression in cultured astrocytes is enhanced by lactic acidosis induced by ischemia which activates the anaerobic glycolytic pathway for synthesis of ATP." (PMID 25904843, 2015). "In a model of MCAO and reperfusion, infusion of propofol prior to ischemia decreased brain edema and reduced over-expression of AQP4." (PMID 25904843, 2015). "Recently, a pharmacological blocker of AQP4, which is also an inhibitor of Na+-K+-2Cl- cotransporter, has been shown to reduce edema post-ischemia at the 24-hour time point; however, the beneficial effect is reversed at 48 hours." (PMID 26526878, 2015). "Aquaporin 4 (AQP4), the main aqueduct in the brain, has emerged as an important target for in vivo and in vitro research focused on brain edema caused by ischemia, intracerebral hemorrhage, brain trauma, hyponatremia, and hepatic encephalopathy." (PMID 25264602, 2014). "Immunofluorescence staining and Western blotting results showed a significant decrease in the expression of AQP4 after treadmill ischemia following pre-training." (PMID 24416250, 2014). "The participation of the perivascular AQP4 pool in generating edema following ischemia was described in vivo in α-Syn−/− mice after middle cerebral artery occlusion." (PMID 25426721, 2014). "Astroglial overexpression of AQP4 in mice accelerates ischemia-induced brain edema, and AQP4 knockdown in traumatized astroglial cultures reduces cell swelling." (PMID 25029343, 2014). "Aquaporin-4 null mice were protected from ischemia-induced retinal functional impairment and cell death." (PMID 23800383, 2013). "The absence of AQP4 in knockout mouse models is known to exacerbate the recovery from vasogenic edema, and AQP4 has been shown to mediate cerebral edema in various models of neurological injury, including epilepsy, ischemia, and trauma." (PMID 22363840, 2012). "It has been shown that the deletion of AQP4 gene can protect retina against swelling in a mouse model of ischemia, thus emphasizing the importance of AQP4 in water transport." (PMID 21298100, 2011). "Another membrane protein that is critically involved in brain edema is aquaporin 4 (AQP4) although other aquaporins (AQP1 and AQP9) have been associated with increased edema following ischemia." (PMID 22174658, 2011). "Evidence from rodent models shows that AQP4 exacerbates cytotoxic edema in acute ischemia by promoting intracellular water influx into astrocytes, whereas in vasogenic edema, it supports fluid reabsorption and glymphatic clearance, thereby alleviating brain swelling." (PMID 40943104, 2025).